IL1B (interleukin 1 beta)
Diseases named in the same sentence as IL1B in open-access papers (continued):
Sharing a sentence is not in itself a finding about the gene and the disease.
Sepsis (continued). "ApoE inhibited the lipopolysaccharide (LPS)-induced increase of tumor necrosis factor-α, interleukin (IL)-1β and IL-6 in serum and decreased the mortality rates of mice with sepsis." (PMID 25242054, 2014). "Interleukin-1 (IL-1) family is a critical mediator of immune response to sepsis with two agonists (IL-1α and IL-1β) and one antagonist (IL-1 receptor antagonist: IL-1ra)." (PMID 24428862, 2014). "The NLRP3 inflammasome is an intracellular multi-protein complex that triggers caspase-1 mediated maturation of interleukin-1β (IL-1β); one of the most potent mediators of inflammation and a major cytokine produced during severe infections, like sepsis." (PMID 25400921, 2014). "The characteristic cytokine markers of sepsis, including IL-1β, IL-6, IL-10 and TNF-α, increased significantly during the experimental timeline." (PMID 24725742, 2014). "Interleukin (IL)-1β is a powerful cytokine that has been reported to be involved in sepsis-induced myocardial dysfunction." (PMID 25216263, 2014). "Biomarkers of sepsis include cytokines such as interleukin 1B (IL1β; Sankar & Webster 2012), as well as other receptor and cell marker biomarkers." (PMID 24578293, 2014). "Further, we show that blockade of the NLRP3 inflammasome/caspase-1/IL-1β pathway can afford protection against lethality in a model of polymicrobial sepsis." (PMID 25216263, 2014). "The release of proinflammatory cytokines (TNF-α and IL-1β) leads to cardiac depression or dysfunction following sepsis." (PMID 24959004, 2014). "Our results indicated the positive association was observed for IL-1B + 3594C/T in sepsis group patients, for IL-1RN VNTR polymorphism in sepsis, severe sepsis, and septic shock group patients, respectively." (PMID 24428862, 2014). "In a rat model of severe sepsis induced by cecal ligation and incision, inhaled LS has been found to reduce the releases of plasma IL-1β and IL-6 and expression of splenic caspase-3." (PMID 25432865, 2014). "High levels of TNF-α, IL-6, and IL-1β in the BALF have been noted in patients with ALI/ARDS, and the persistent elevation of proinflammatory cytokines in humans with ALI or sepsis has been associated with more severe outcomes." (PMID 25013450, 2014). "Of importance, caspase-1 knockout exhibits the protective effect on a murine sepsis model, where the plasma IL-1β level was completely depressed, suggesting a crucial role of caspase-1 in sepsis." (PMID 24454930, 2014). "As an immunomodulator, visfatin induces dose-dependent up-regulation of the pro- and anti-inflammatory cytokines, IL-1β, IL-6, IL-10, and TNF-α in human monocytes: visfatin is associated with sepsis, acute lung disease, atherosclerosis, and cancer." (PMID 24885580, 2014). "Further, neuroimmunopathogenesis of sepsis involves peripheral release of proinflammatory cytokines (TNF-α, IL-1α, IL-1β, and IL-6) increasing blood brain barrier (BBB) permeability, generating neuroinflammation and sepsis associated sickness behaviour." (PMID 25018890, 2014). "MSCs have been shown to suppress production of pro-inflammatory cytokines and chemokines, including MIP-2(CXCL-2), CCL5, TNF, IL-6, and IL-1β, in animal models of lung injury and sepsis." (PMID 24423010, 2014). "The results demonstrated that the IL-1A-889C/T, IL-1B-3594C/T, and IL-1RN VNTR polymorphisms had significant associations with the risk of sepsis, although some results were limited by the small number of studies." (PMID 24428862, 2014). "The previous experiments showed that TNF-α and IL-1β were important inflammatory cytokines during sepsis, which were mainly produced by activated macrophages and cardiomyocytes." (PMID 24959004, 2014). "Although our findings strongly support a role for the NLRP3 inflammasome/caspase-1/ IL-1β pathway of CFs in the myocardial dysfunction, as well as, lethality in sepsis, extrapolation to the human condition is rather tenuous." (PMID 25216263, 2014).
Sepsis (continued). "Consistent with the notion that lipopolysaccharide (LPS)-induced caspase 11 activates interleukin 1β (IL1β) secretion, a TRPC1-/- sepsis model showed increased secretion of IL1β after LPS challenge." (PMID 25268281, 2014). "Sepsis is caused by a systemic response to infection, which is characterized by elevated levels of proinflammatory cytokines such as TNF-α, IL-1β, IFNγ and IL-6 in the circulation or in inflamed tissues." (PMID 25269519, 2014). "We show for the first time, in an experimental model of sepsis, that glyburide acts as an anti-inflammatory agent by reducing IL1β secretion, cellular infiltration into the lungs and bacterial dissemination to distant organs." (PMID 24147174, 2013). "TNF-α and IL-1 (a term used for a family of proteins, including IL-1α and IL-1β) are among the most extensively studied cytokines in sepsis pathophysiology." (PMID 23853427, 2013). "IL-1β and IL-10 concentrations are significantly higher in patients with septic shock than in those with severe sepsis." (PMID 23675299, 2013). "Second, Il-1r−/− mice exhibited lower serum and peritoneal IL-10 and C5a levels during sepsis, although IL-1β levels were similar in Il-1r−/− and WT mice." (PMID 23675299, 2013). "Recent studies have suggested the novel importances of IL1β and High Mobility Group Box 1 on the development of cognitive impairment in sepsis survivors." (PMID 23718252, 2013). "The first group is the early proinflammatory mediators, such as TNF-α and IL-1β, which are induced within hours after the induction of sepsis." (PMID 24098466, 2013). "Clinically relevant doses of PCT, similar to those achieved in sepsis, induced the secretion of the pro-inflammatory cytokines TNFα, IL-1β and IL-6 in whole human blood cells in vitro." (PMID 23937962, 2013). "In fact, studies showed that proinflammatory cytokines such as IL-1β and reactive species have been shown to decrease the expression of Na+, K+-ATPase during severe experimental sepsis." (PMID 24205200, 2013). "Early microglial activation in sepsis was evidenced in mice models within 4 hours following LPS injection, as assessed by the increased proinflammatory cytokine IL1β level in microglia." (PMID 23718252, 2013). "Fifth, neutrophil depletion in WT mice reduced the levels of IL-1β, IL-10, and C5a, although these depletion effects were dependent on time points of sepsis." (PMID 23675299, 2013). "To estimate cytokine-mediated effector functions of immune cells in sepsis, we measured the expression of IL-1β and IL-10 receptors on peritoneal cells." (PMID 23675299, 2013). "We now show for the first time in any model of sepsis that glyburide acts as an anti-inflammatory agent by reducing IL1β secretion, cellular infiltration into the lungs and bacterial dissemination to distant organs." (PMID 24147174, 2013). "In conclusion, NOD2-mediated signals increase C5a levels by suppressing CD55 expression on neutrophils via IL-1β-dependent or IL-1β-independent IL-10 production by neutrophils, thereby aggravating sepsis." (PMID 23675299, 2013). "It generally accepted that IL-1β-mediated systemic inflammatory responses and cardiac dysfunction, and IL-10-mediated immune suppression account for the high mortality in sepsis." (PMID 23675299, 2013). "TNF-α, IL-6 and IL-1β are the most important endogenous mediators in the sepsis process, the measurement of which can be helpful in the determination of sepsis severity." (PMID 24250599, 2013). "Inflammasome activation is exclusively responsible for caspase-1-mediated IL-1β and IL-18 maturation and secretion in immune cells, and circulating IL-1β and IL-18 levels are known to be increased in critically ill patients with both sepsis and ARDS." (PMID 24391478, 2013). "Our results indicate that NOD2-mediated signals enhance C5a generation by suppressing CD55 expression on neutrophils through IL-1β-dependent or IL-1β-independent IL-10 production during polymicrobial sepsis." (PMID 23675299, 2013).
Sepsis (continued). "Upon SB203580 injection, WT mice exhibited reduced RIP2 expression and phosphorylation, and P38 phosphorylation in total peritoneal cells and serum and peritoneal IL-1β, IL-10, and C5a levels during sepsis, whereas these were unaffected in Nod2−/− mice." (PMID 23675299, 2013). "We further show, for the first time in any model of sepsis, that glyburide acts as an anti-inflammatory agent by reducing IL1β secretion accompanied by diminished cellular influx and reduced bacterial dissemination to distant organs." (PMID 24147174, 2013). "IL-6 is an early mediator and has a longer half-life period than TNFα and IL-1β and that intrinsic property makes it possible to use IL-6 as a marker of sepsis and SIRS." (PMID 24049646, 2012). "In this study, we demonstrated a significant increase in gene production of proinflammatory cytokines, including TNF-α and IL-1β, in brain tissues of mice at 12–24 h after sepsis induction by CLP." (PMID 23236515, 2012). "In keeping with these results, our study also found a significant reduction of the systemic IL-1β release in animals with CASP-induced sepsis treated with the CB2R agonist HU308." (PMID 22420504, 2012). "We have proceeded to show that stimulation of NOD1 in human endothelial cells induces multiple chemokine and cytokine response genes that are implicated in sepsis including CXCL6, CXCL8, IL1-β and TNFα." (PMID 22870324, 2012). "Increased phosphorylation at Y658 in endotoxemia by MAT.Ang-1, in addition to reduced IL-1β expression, is therefore likely to reduce neutrophil infiltration and microvascular stasis in sepsis." (PMID 23036162, 2012). "Subsequent studies indicated TNF-α and IL-1β as the pivotal mediators inducing cardiac depression in sepsis and other disease conditions." (PMID 22577249, 2012). "IL-6 is one of the first acute phase cytokines released in sepsis/endotoxemia and is followed by increases in the levels of IL-1β, IL-8, TNF-α and IL-10." (PMID 23078757, 2012). "Both polymicrobial sepsis and intratracheally lipopolysaccharide (LPS) injection can induce acute lung inflammation with elevated IL-1β, KC, MIP-2 levels and MPO activity of lung in mice." (PMID 21906393, 2011). "The aim of the present study is to define if defective production of IL-1β from monocytes in clinical sepsis is due to down-regulation of gene expression or inhibition of the inflammasome." (PMID 21244670, 2011). "Depending on this view, exogenous administration of rmMFG-E8 attenuated inflammation by reducing pro-inflammatory cytokines, TNF-α, IL-6 and IL-1β in sepsis as well as other diseases where LPS-TLR4 signaling is predominant." (PMID 22114683, 2011). "To this end, we investigated the down regulation of IL-1β in sepsis and experimental endotoxemia in human volunteers with emphasis on the activation of caspase-1 and subsequent IL-1β production." (PMID 21244670, 2011). "The pattern of production of IL-1β is different from that with TNFα, as IL-1β is being down-regulated both in severe sepsis and in uncomplicated sepsis, while TNFα production is sustained in this last category of patients." (PMID 21244670, 2011). "The mRNA expressions of IL-6 and IL-1β in lung tissue were determined due to the role of these markers in the pathogenesis of sepsis and ventilator-induced lung injury (VILI)." (PMID 20546573, 2010). "Clinical and experimental studies suggest that cytokines, especially TNFα, IL-1β and IL-6 appear to play a pivotal role in mediating the hemodynamic effects and the release of cardiac troponin in patients with severe sepsis and septic shock." (PMID 20140242, 2010). "In this respect, the profile of systemic cytokines' changes in response to exercise differs from that observed in sepsis, where there is a relevant increase in both serum IL-1β and IL-1ra." (PMID 20175886, 2010).
Sepsis (continued). "We found that in vivo neutralization of endogenous MCP-1 during acute sepsis led to substantial decreases in the transcript levels for IL-1α, IL-1β, and IL-6, as well as MCP-1 itself, in the diaphragm." (PMID 20950459, 2010). "For example, while neutralization of ether TNF-α or IL-1β has little effect on mortality in humans or in mice subjected to lethal polymicrobial sepsis via Cecal Ligation and Puncture (CLP), combined neutralization does improve survival in CLP." (PMID 19672303, 2009). "This is characterized by an initial burst of pro-inflammatory cytokines, such as IL-6, TNF-α and IL-1β, which in controlled settings, can recapitulate many of the clinical findings of sepsis." (PMID 19672303, 2009). "Pro-inflammatory cytokine production such as TNF-α and IL-1β in the early phase of sepsis has the potential to activate NF-κB and other transcription factors that are key in the reactivation of CMV from latency." (PMID 19442306, 2009). "Studies have also shown that circulating concentrations of TNF-α, IL-1β, and IL-6 increase significantly in the early, hyperdynamic stage of sepsis and remain elevated in the late, hypodynamic stage of sepsis." (PMID 18680601, 2008). "Sepsis enhanced the transcription of several pro- and anti-inflammatory cytokines and chemokines including tumor necrosis factor alpha, interleukin-1 beta, transforming growth factor beta, and monocot chemoattractant protein 1 in the cerebrum." (PMID 18793399, 2008). "Additionally, sepsis patients with CG/GG genotypes expressed significantly increased levels of IL-1β, IL-6, and ICAM-1 than those with CC genotype." (PMID 42311758, 2026). "Additionally, DYY inhibited inflammation (TNF-α, IL-1β, and IL-6), cell apoptosis, and promoted proliferation in sepsis, as well as the promotion of tight junction proteins (claudin-1, occludin, and ZO-1)." (PMID 41948377, 2026). "Also, based on the in vivo experiments, the deficient of GAT2 together with the pharmacological inhibition regarding de novo serine synthesis in vivo weaken the IL-1β level induced by LPS, and increase the sepsis survival rate in related LPS-driven model." (PMID 38123749, 2025). "IL-1β and TNF-α are major inflammatory cytokines involved in the acute inflammatory response, and higher levels are associated with an increased risk of postoperative infection, systemic inflammatory response syndrome, and sepsis." (PMID 40142333, 2025). "Strategically, inhibiting key palmitoylation-related processes involved in GSDMD-induced macrophages pyroptosis and IL-1β release could attenuate sepsis-induced organ injury." (PMID 40461967, 2025). "Additionally, due to the limited availability of patient sera, we were unable to detect other biomarkers associated with sepsis, such as TNF-α, IL-1β, and IL-8." (PMID 40176879, 2025). "In clinical experiments, we measured plasma levels of TIFA and IL-1β in patients with sepsis." (PMID 40385253, 2025). "Furthermore, macrophages play a crucial role in the liver damage caused by elevated levels of IL-1β and TNF-α both in the liver and serum of LPS-induced sepsis mice." (PMID 40298842, 2025). "As a bait receptor for IL-1β, IL-1R2 has a two-fold function in the pathophysiology of sepsis." (PMID 40699828, 2025). "Moreover, it must be noted that most data on TNF-α/IL-1β/mediated myocardial injury come from sepsis, ischemia-reperfusion, or animal models." (PMID 40710793, 2025). "Notably, inflammatory cytokines including TNF-α, IL-1β, and IL-6 serve as critical regulators in sepsis pathogenesis." (PMID 40775729, 2025). "Experiments conducted both in a laboratory setting and in living organisms demonstrated a notable increase in the levels of NLRP3 and IL-1β expression in Kupffer cells in a sepsis model induced by LPS, highlighting their strong response to the pyroptosis pathway." (PMID 40458798, 2025). "Moreover, sepsis induction leads to the generation of proinflammatory cytokines such as IL-1β, IL-18, and TNF-α." (PMID 40770673, 2025).
Sepsis (continued). "Notably, clopidogrel has recently demonstrated efficacy in suppressing platelet inflammasome activation, thereby reducing the release of IL-1β and IL-18 and improving renal outcomes in sepsis models." (PMID 40692784, 2025). "The identification of TNF and IL1B as bridging proteins between systemic inflammation and neurological processes, combined with respiratory-centric disease enrichment patterns, provides mechanistic insights into sepsis pathophysiology." (PMID 41299255, 2025). "Additionally, mitotherapy involving repetitive injections after CLP resulted in a significant decrease in the IL-1β level when compared to the Sepsis+Mito1 group (P=0.0005)." (PMID 40584438, 2025). "Furthermore, ALA protected BBB permeability, decreased neuroinflammation by reducing TNF-α and IL-1β levels and acutely increased antioxidant activity in brain structures after sepsis induction." (PMID 40077661, 2025). "Similarly, IL-1β is recognized as a central instigator of the cytokine storm, amplifying inflammatory cascades and correlating strongly with sepsis severity and prognosis." (PMID 40722817, 2025). "Similarly, mRNA levels of proinflammatory mediators, including TNF-α, IL-1β, and IL-6, were upregulated in the lung tissue following sepsis." (PMID 40421173, 2025). "In our polymicrobial sepsis model, at 2 hours post-infection, we found that fluoxetine-pretreated mice had equivalent induction of TNFα and IL-6 and significantly higher levels of serum IL-1β compared to vehicle-treated infected mice." (PMID 39951524, 2025). "Similarly, while M1mAChR-mediated orexinergic enhancement reduced serum levels of TNFa and IL-1b, elevated levels of other cytokines believed to play a key role in sepsis pathobiology (eg, IL-6) respond to orexin via a mechanism that is M1mAChR independent." (PMID 40909798, 2025). "Moreover, the elevated NGAL and KIM‐1 levels in serum, TNF‐α, IL‐6, and IL‐1β levels in the kidneys in sepsis group were partly reversed by LV‐shMALAT1." (PMID 39390627, 2024). "Likewise, the occupancy by H3S28p was increased in TNFA and IL-1B promoters at 1 dpb in patients who developed sepsis." (PMID 39768289, 2024). "The collective action of these functions exacerbates systemic inflammatory response, and research has demonstrated that levels of IL-1β are elevated in sepsis non-survivors in comparison to survivors, indicating a relationship between heightened IL-1β levels and sepsis outcomes." (PMID 39252831, 2024). "Immunomodulatory agents may hold promise, given the significance of TNF-α and IL-1β as sepsis mediators." (PMID 39200042, 2024). "In sepsis, crucial pro-inflammatory cytokines are IL-1β, IL-6, IL-12, and IL-17." (PMID 39063011, 2024). "Moreover, evidence suggests, in the presence of IL-1β, EV miR-21 can efficiently stimulate macrophages towards M2 polarization, both in vitro and in vivo, resulting in therapeutic effects against sepsis." (PMID 38922501, 2024). "IL-1β also inhibits the normal differentiation of OPCs in postnatal sepsis rats." (PMID 38665289, 2024). "In the bone marrow, we confirmed that TNF plus IL-1β are sufficient to decrease the abundance of cell types from the erythroid lineage, which help to explain anemia, a well-described phenomenon in sepsis." (PMID 38191855, 2024). "Indeed, we and others have reported that CLP-sepsis causes both the activation of NLRP3 inflammasome and proteolytic cleavage of pro-caspase-1 to its active form caspase-1, finally leading to IL-1β maturation and release." (PMID 39559354, 2024). "Similarly, Yao and colleagues demonstrated that macrophages are polarized into M2 phenotype by miR-21 transferred from MSC-derived EVs pre-treated with IL-1β, which significantly enhanced the therapeutic effects in experimental sepsis." (PMID 38247814, 2024).